ICOS (inducible T cell costimulator)
Diseases named in the same sentence as ICOS in open-access papers (continued):
Sharing a sentence is not in itself a finding about the gene and the disease.
experimental autoimmune encephalomyelitis (3 papers, 2015 to 2024). An autoimmune demyelinating disease of the central nervous system that is produced experimentally in animals by the injection of homogenized brain or spinal cord in Freund's adjuvant. "Previous studies showed that ICOS-knockout (KO) mice exhibit severe experimental autoimmune encephalomyelitis (EAE), the animal model of MS, but data on ICOSL deficiency are not available." (PMID 38473756, 2024). "ICOS-deficient mice develop increased numbers of Vγ4+ cells than WT controls, and experimental autoimmune encephalomyelitis is more severe in these mice as a result of increased IL-17A levels." (PMID 36480166, 2023). "Inducible T cell costimulator (ICOS) signaling is important in thymic development of IL-17A–producing γδ T cells and function during experimental autoimmune encephalomyelitis, while the function of PD-1 on these cells is unknown." (PMID 36480166, 2023).
heart failure (3 papers, 2023 to 2025). Inability of the heart to pump blood at an adequate rate to meet tissue metabolic requirements. "Furthermore, inhibition of T cell–specific ICOS or EC-specific ICOS ligand prevented cardiac fibrosis development in a preclinical heart failure and myocarditis models." (PMID 40401523, 2025).
Hepatitis (3 papers, 2018 to 2025). Inflammation of the liver. "Here, circulating CD4+ T cells with high programmed cell death 1 (PD-1) and ICOS coexpression were temporally associated with onset of virus control, seroconversion, and hepatitis in HCV-infected chimpanzees." (PMID 40956619, 2025). "In addition, the proportion of ICOS+Tfh cells was lower in healthy adults who did not receive hepatitis B vaccination or had a weak response to it, suggesting that Tfh cells and ICOS are involved in humoral immunity and promote the production of anti-HBs antibodies." (PMID 38555445, 2024).
Hodgkins lymphoma (3 papers, 2022 to 2024). A heterogeneous group of malignant lymphoid neoplasms of B-cell origin characterized histologically by the presence of Hodgkin and Reed-Sternberg (HRS) cells in the vast majority of cases. "In another study, CXCR5+ ICOS+ CD8 T cells had been shown to infiltrate tumoral lymph nodes (LNs) in Hodgkin lymphoma (HL)." (PMID 36172358, 2022). "In addition, another study found that CXCR5+ICOS+CD8+ T cells show significant infiltration in tumor lymph nodes (LNs) of patients with Hodgkin’s lymphoma (HL) and could upregulate the expression of IL-2, IL-4, and IL-21, which promotes B-cell proliferation and antibody production." (PMID 38515134, 2024). "In the group of patients presenting a nodular sclerosis subtype, the immune profile switched at relapse, with an upregulation of LGALS1 and TGFB1 and downregulation of CD163, CD274, HGF, IL15, and ICOS." (PMID 36230815, 2022).
nephritis (3 papers, 2016 to 2022). Inflammation of renal tissue. "Using multicolor fluorescence histochemical staining on renal biopsy tissues of patients with IgAN, we revealed that Tfh cells (CD4+ICOS+) were present in the kidney and mainly distributed around the glomeruli affected by nephritis." (PMID 35983053, 2022). "In this study, CD4+ CXCR5+ and CD4+ CXCR5+ ICOS+ Tfh cells were abnormally elevated in children with non-nephritis-type HSP, and were significantly associated with PGA-IgA, especially CD4+ CXCR5+ ICOS+-activated Tfh cells." (PMID 34250253, 2021).
oral squamous cell carcinoma (3 papers, 2024 to 2025). "In particular, tumors expressing high levels of ICOS show increased immune cell infiltration, and ICOS is a positive prognostic factor in the B7 immune checkpoint co-stimulatory factor family in HNSCC and oral squamous cell carcinoma." (PMID 40661938, 2025).
papillary thyroid cancer (3 papers, 2016 to 2023). "As reported in gastric and papillary thyroid cancer, there were clues that plasmacytoid dendritic cells induce Tregs, especially ICOS+ Tregs, through the ICOS−ICOSL pathway." (PMID 27725696, 2016). "Conversely, in papillary thyroid cancer most checkpoint molecules, including LAG-3, PD-1, inducible T cell COStimulator (ICOS), and indoleamine 2,3-Dioxygenase 1 (IDO1), were significantly decreased compared with healthy thyroid tissues." (PMID 36077354, 2022). "In papillary thyroid carcinoma (PTC), which is the most common form of well-differentiated thyroid cancer, most checkpoint molecules, including LAG-3, PD-1, ICOS, and IDO1, are significantly reduced compared to TIM-3, whose expression is significantly enriched." (PMID 37567938, 2023).
pemphigus (3 papers, 2016 to 2023). Pemphigus is a group of rare autoimmune diseases that cause blistering of the skin and mucous membranes (mouth, nose, throat, eyes, and genitals).This conditioncan occur at any age, but often strikes people in middle or older age. "In addition, Dsg3‐specific Tfh cells were detected using I‐Ab tetramer with Dsg3 (516–530 aa) peptide highly expressed ICOS, and ICOS blockade reduced anti‐Dsg3 antibody production in the model, demonstrating pivotal roles of Dsg3‐specific ICOS+CXCR5+PD‐1+ Tfh cells in the pemphigus mouse model." (PMID 36539957, 2023).
Sepsis (3 papers, 2022 to 2025). Sepsis is defined as life-threatening organ dysfunction caused by a dysregulated host response to infection. "Fittingly, we have recently reported that, in a mouse model of sepsis, ICOS-deficient mice display a striking increase in blood IL-6 levels, which are substantially decreased by ICOS-Fc treatment." (PMID 36769276, 2023). "Administration of ICOS-Fc to WT CLP mice reduced all of these abnormalities caused by sepsis." (PMID 36119089, 2022). "Collectively, our data show the beneficial effects of pharmacological modulation of the ICOS-ICOSL pathway in counteracting the sepsis-induced inflammation and organ dysfunction." (PMID 36119089, 2022). "A greater understanding of the molecular basis of ICOS-Fc-mediated effects is needed to harness its actions as a potentially powerful immunomodulatory tool for counteracting inflammation and organ injury in sepsis." (PMID 36119089, 2022). "Thus, we investigated the pathological role of the ICOS-ICOSL axis in the context of sepsis and the potential protective effects of its immunomodulation by administering ICOS-Fc in a murine model of sepsis." (PMID 36119089, 2022). "Moreover, sepsis was induced in mice deficient for ICOS, ICOSL, or OPN to assess the role the endogenous molecules of the ICOS/ICOSL/OPN system." (PMID 36119089, 2022). "Thus far, the role of ICOS-ICOSL interaction has been poorly investigated in sepsis, although recent findings report that ICOS expression is reduced in whole blood of septic patients, and that reduced ICOS levels are strongly associated with organ dysfunction." (PMID 36119089, 2022). "However, treatment with ICOS-Fc significantly decreased IL-1β and TNF-α in WT mice and IL-1β, IL-6 and IL-10 in ICOS-/- mice indicating that ICOS-Fc substantially downmodulates the cytokine storm in sepsis." (PMID 36119089, 2022). "Therefore, here we investigated, for the first time, the pathological role of ICOS-ICOSL axis in the context of sepsis, its impact on selective inflammatory pathways and the potential protective effects of its immunomodulation by administering ICOS-Fc in an experimental model of sepsis." (PMID 36119089, 2022). "Analysis of CLP knockout mice showed that ICOS-/- and ICOSL-/- mice showed similar clinical scores and decreased body temperatures as WT mice, whereas OPN-/- mice developed milder sepsis, with lower clinical scores and higher body temperature than WT mice." (PMID 36119089, 2022). "Polymicrobial sepsis was induced by cecal ligation and puncture (CLP) in five-month-old male wild-type (WT) C57BL/6, ICOS-/-, ICOSL-/- and OPN-/- mice." (PMID 36119089, 2022). "In conclusion, we demonstrate here, for the first time, that the ICOS-ICOSL axis plays a crucial role in the development of systemic inflammation and organ damage induced by a clinically relevant sepsis model." (PMID 36119089, 2022).
squamous cell carcinoma (3 papers, 2017 to 2021). A carcinoma arising from squamous epithelial cells. "This is also relevant for the potential role of ICOS in tumor surveillance for virally induced tumors, highlighted by the HPV-associated vulvar carcinoma in patient #1 and the squamous cell carcinoma in patient #6." (PMID 28861081, 2017).
thymoma (3 papers, 2022 to 2024). A neoplasm arising from the epithelial cells of the thymus. "Strikingly, in THCA and THYM (thymoma), NEIL3 was significantly associated with more than 20 immune checkpoint genes, such as CD86, ICOS, TNFSF4, and CD48, implying its role in regulating the tumor immune microenvironment." (PMID 36612106, 2022).
angioimmunoblastic T-cell lymphoma (2 papers, 2023). A mature T-cell non-Hodgkin lymphoma, characterized by systemic disease and a polymorphous infiltrate involving lymph nodes and extranodal sites. "The evaluation of the effectiveness of anti-ICOS ADCs in patient-derived xenografts from individuals with SS and angioimmunoblastic T-cell lymphoma yielded promising results." (PMID 36765704, 2023).
autoimmune type 1 diabetes (2 papers, 2020 to 2023). Autoimmune disease wherein the body's own immune system attacks and destroys the cells within the pancreas that produce insulin. "In experimental models of allergic encephalomyelitis (EAE) and autoimmune type 1 diabetes, blockade of ICOS/ICOSL is associated to severe worsening of the diseases." (PMID 36865548, 2023). "Indeed, in NOD mice, ICOS deficiency protects against the spontaneous development of autoimmune type 1 diabetes but results in the development of neuromuscular autoimmunity associated with inflammatory cell infiltrates in the CNS." (PMID 32414808, 2020).
cholangiocarcinoma (2 papers, 2024 to 2025). A carcinoma that arises from the intrahepatic biliary tree (intrahepatic cholangiocarcinoma) or from the junction, or adjacent to the junction, of the right and left hepatic ducts (hilar cholangiocarcinoma). "Our findings provide novel insights into tumor-immune interactions in cholangiocarcinoma and suggest the ICOS–ICOSL axis as a potential therapeutic target for immunotherapy." (PMID 41180156, 2025). "Notably, we identified enhanced ICOS signaling between dendritic cells and T cells as a prominent feature of cholangiocarcinoma." (PMID 41180156, 2025).
chronic GVHD (2 papers, 2017 to 2018). "To date, there is no clinical evidence that ICOS polymorphisms are associated with acute or chronic GVHD, but larger studies covering the entire ICOS and ICOS-L locus in non-ethnical biased studies are warranted before any conclusions can be drawn." (PMID 28713380, 2017).
Cognitive impairment (2 papers, 2022 to 2025). Abnormal cognition is characterized by deficits in thinking, reasoning, or remembering. "Patients with creatinine <60.75 (μmol/L), chloride <106.25 (mmol/L), CD4+ICOS+ ≥11.2%, CD19+PD-L1+ ≥12.35%, plasma sICOSL≥286.37 ng/mL, CSF sugar content ≥3.775 (mmol/L), and those with cognitive impairment are more likely to be diagnosed with AE." (PMID 40352922, 2025). "Patients with elevated levels of CSF glucose and plasma sICOSL, increased percentages of peripheral blood CD4+ICOS+ and CD19+PD-L1+, and symptoms of cognitive impairment were more likely to be diagnosed with AE." (PMID 40352922, 2025). "In contrast, abnormal psychological behaviors, cognitive impairments, serum LDH, serum calcium, CSF glucose, serum oligoclonal bands (OCBs), CD4+ICOS+, CD4+CXCR5+ICOS+, CD19+PD-L1+, and plasma sICOSL were more prominent in the early AE group." (PMID 40352922, 2025). "For example, consider a patient with the following characteristics: cognitive impairment (15 points), CD4+ICOS+ of 30% (22.5 points), CD19+PD-L1+ of 80% (27.5 points), plasma sICOSL of 500 ng/mL (40 points), and CSF glucose of 8 mmol/L (40 points)." (PMID 40352922, 2025). "Furthermore, we developed an early differential diagnosis model based on serum creatinine, chloride, peripheral blood CD4+ICOS+, CD19+PD-L1+, plasma sICOSL, CSF glucose, fever, nausea and vomiting, headache, and cognitive impairment." (PMID 40352922, 2025).
colon adenocarcinoma (2 papers, 2021 to 2023). "Numerous malignancies, including colon adenocarcinoma (COAD), endocervical adenocarcinoma (CESC), and lung adenocarcinoma(LUAD), have been linked to the upregulation of ICOS." (PMID 36855091, 2023).
combined immunodeficiency (2 papers, 2017 to 2021). A broad classification of inherited disorders presenting at birth that affect both the cell-mediated and humoral aspects of the immune response. "In some patients with ICOS deficiency, the pattern of viral susceptibility rather suggests a combined immunodeficiency (CID)." (PMID 28861081, 2017).
cutaneous T cell lymphoma (2 papers, 2021 to 2023). "Previous studies have reported that ICOS is widely expressed in cutaneous T cell lymphoma and can target and potently kill malignant cells." (PMID 33869632, 2021). "To summarize, in cutaneous T-cell lymphomas, the overexpression of ICOS by malignant T cells and Treg cells suggests that depletion of ICOS-expressing cells could both directly reduce the tumor cell burden and activate the antitumor immune responses by killing Tregs." (PMID 36765704, 2023).
cyst (2 papers, 2020 to 2024). A sac-like closed membranous structure that may be empty or contain fluid or amorphous material. "We also examined the reduction in the cyst burdens of the recipients of the WT and ICOS−/− CD8+ T cells by using immunohistochemical staining for T. gondii on their brains." (PMID 39682747, 2024). "This increase in cyst number was further shown in H&E stained histology sections from the brains of chronically infected WT, ICOS KO, and ICOS YF mice." (PMID 31978191, 2020). "Notably, the cyst numbers in the recipients of the ICOS−/− CD8+ T cells were significantly lower than those of the WT CD8+ T cell recipients (p < 0.01)." (PMID 39682747, 2024). "Indeed, both ICOS KO and ICOS YF mice had significantly increased parasite cyst burdens in the brain compared to WT controls." (PMID 31978191, 2020). "Interestingly, while chronically infected WT mice usually have single parasite cysts in isolation from others, both ICOS KO and ICOS YF mice had and increased incidence of parasite cyst “clusters”, where multiple cysts were found in close proximity to each other in the inflamed brain." (PMID 31978191, 2020). "Since perforin is required for the anti-cyst effector activity of CD8+ T cells, we compared the expression levels of mRNA for perforin in the ICOS−/− and WT CD8+ T cells that had migrated into the brains of infected SCID mice after receiving the transfer of those T cells." (PMID 39682747, 2024). "The results of the present study may also suggest that, in the presence of CD28 expression, the increased expression of ICOS in WT CD8+ T cells, as detected in our recent study, could enhance their anti-cyst effector activity, allowing them to eliminate T. gondii cysts." (PMID 39682747, 2024).
dengue (2 papers, 2020 to 2024). "In our study, PD-1 and ICOS co-expressing Tfh cells were significantly expanded (p < 0.0001) in patients with acute dengue compared to healthy individuals." (PMID 32264870, 2020).
encephalitis (2 papers, 2023 to 2025). An acute inflammatory process affecting the brain parenchyma. "The serum of patients with LGI1 encephalitis had reduced levels of CD28, ICOS-L, PDCD1 (all p < 0.05), and CD86 (p < 0.01), but higher levels of ICOS (p < 0.05) and PD-L2 (p < 0.001) were detected." (PMID 37644514, 2023). "Similarly, ICOS and PD-L2 were found at a higher concentration in the serum of LGI1 encephalitis patients, whereas four ICMs were detected at a lower concentration compared to HDs." (PMID 37644514, 2023).
endothelial dysfunction (2 papers, 2022 to 2025). In vascular diseases, endothelial dysfunction is a systemic pathological state of the endothelium (the inner lining of blood vessels) and can be broadly defined as an imbalance between vasodilating and vasoconstricting substances produced by (or acting on) the endothelium. "T cells expressing ICOS may directly interact with endothelial cells expressing ICOS-L; notably, it has been shown that stressful stimuli, such as advanced glycation end products (AGEs), can lead to overexpression of ICOS-L on endothelial cells leading to endothelial dysfunction." (PMID 35328257, 2022).
eosinophilia (2 papers, 2009 to 2017). "Further phenotypic changes occurred during this IL-2/Jes6-1 treatment, namely an expanded population of IL-5+ ILC2 (Lin− ICOS+), associated eosinophilia and decreased CD11b+ Ly6G− Ly6Chi inflammatory monocytes." (PMID 28589929, 2017). "The decreased immune response and lung eosinophilia observed in the ICOS+/− mice may also be caused by decreased activation of ICOS+/− T cells." (PMID 19888475, 2009). "Herein we demonstrate that ICOS+/− mice have decreased Th2 immune responses in vivo resulting in decreased airway eosinophilia and defective T cell cytokine production." (PMID 19888475, 2009). "The ICOS+/− mice had decreased cellular infiltrates in the airways, decreased airway eosinophilia, decreased serum IgE, and defective Th2 cytokine production upon in vitro restimulation of T cells from the lungs and draining lymph nodes." (PMID 19888475, 2009). "The finding that ICOS+/− mice have decreased lung eosinophilia led us to hypothesize that T cells from these mice have defects in Th2 differentiation and/or effector function." (PMID 19888475, 2009).
Granuloma (2 papers, 2013 to 2015). A compact, organized collection of mature mononuclear phagocytes, which may be but is not necessarily accompanied by accessory features such as necrosis. "All these studies are in line with ours; however, ICOS deficiency or blocking ICOS has been reported to no change or increase in the size of egg induced granulomas during S. mansoni infection." (PMID 25590646, 2015). "Similarly, although Ab mediated blockade of ICOS has been reported to increase granulatomous responses to S. mansoni eggs 34, there was no change in the size of egg-induced granulomas during S. mansoni infection." (PMID 23319295, 2013).
interstitial lung disease (2 papers, 2022 to 2025). A diverse group of lung diseases that affect the lung parenchyma. "We herein investigated the efficacy of acazicolcept (ALPN-101), a dual ICOS/CD28 antagonist, in two complementary SSc-related mouse models recapitulating skin fibrosis, interstitial lung disease, and pulmonary hypertension." (PMID 34986869, 2022).
leukemia (2 papers, 2021). A malignant (clonal) hematologic disorder, involving hematopoietic stem cells and characterized by the presence of primitive or atypical myeloid or lymphoid cells in the bone marrow and the blood. "High expression of ICOS in leukemia was associated with poor prognosis and might contribute to tumor proliferation by assisting tumor cells in evading antitumor immune responses." (PMID 34434928, 2021).
Listeria infection (2 papers, 2015 to 2016). "In the same manner, disruption of ICOS signaling during oral Listeria monocytogenes infection via ICOS–Ig treatment led to decreased Th1 immunity and significantly increased splenic bacterial burden and lethality." (PMID 27559335, 2016). "The ability of our ICOS protein to signal was confirmed in separate studies which showed that expression of this construct functioned to increase CD8+ T cell expansion and alter memory differentiation in a model of Listeria infection (data not shown)." (PMID 26098894, 2015).